ELOB (elongin B)
Description:
SIII, also known as elongin, is a general transcription elongation factor that increases the RNA polymerase II transcription elongation past template-encoded arresting sites. Subunit A is transcriptionally active and its transcription activity is strongly enhanced by binding to the dimeric complex of the SIII regulatory subunits B and C (elongin BC complex). In embryonic stem cells, the elongin BC complex is recruited by EPOP to Polycomb group (PcG) target genes in order generate genomic region that display both active and repressive chromatin properties, an important feature of pluripotent stem cells (By similarity). Core component of multiple cullin-2 and cullin-5-RING E3 ubiquitin-protein ligase complexes (ECS complexes), which mediate the ubiquitination of target proteins. By binding to BC-box motifs it seems to link target recruitment subunits, like VHL and members of the SOCS box family, to Cullin/RBX1 modules that activate E2 ubiquitination enzymes. Component the von Hippel-Lindau ubiquitination complex CBC(VHL). A number of ECS complexes (containing either KLHDC2, KLHDC3, KLHDC10, APPBP2, FEM1A, FEM1B or FEM1C as substrate-recognition component) are part of the DesCEND (destruction via C-end degrons) pathway, which recognizes a C-degron located at the extreme C terminus of target proteins, leading to their ubiquitination and degradation. The ECS(ASB9) complex mediates ubiquitination and degradation of CKB. As part of a multisubunit ubiquitin ligase complex, polyubiquitinates monoubiquitinated POLR2A. ECS(LRR1) ubiquitinates MCM7 and promotes CMG replisome disassembly by VCP and chromatin extraction during S-phase (By similarity). As part of the ECS(RAB40C) complex, mediates ANKRD28 ubiquitination and degradation, thereby inhibiting protein phosphatase 6 (PP6) complex activity and focal adhesion assembly during cell migration. The ECS(ASB7) complex acts a negative regulator of H3K9me3 histone mark by mediating ubiquitination and degradation of SUV39H1. As part of the ECS(LRRC58) complex, mediates CDO1 ubiquitination and degradation, regulating cysteine catabolism. (Microbial infection) Following infection by HIV-1 virus, component of a cullin-5-RING E3 ubiquitin-protein ligase complex (ECS complex) hijacked by the HIV-1 Vif protein, which catalyzes ubiquitination and degradation of APOBEC3F and APOBEC3G. The complex can also ubiquitinate APOBEC3H to some extent.
Synonyms: TCEB2; SIII
Tractability: Small molecule: a structure with a bound ligand is known; a high-quality ligand is known. PROTAC: ubiquitination databases record sites on it; a small molecule that binds it is known.
Gene: Protein-coding gene on chromosome 16 (2,771,414 to 2,777,290, reverse strand). Ensembl gene ENSG00000103363.
Subcellular location: Nucleus
Pathways (Reactome):
Disease: Evasion by RSV of host interferon responses; Formation of HIV elongation complex in the absence of HIV Tat; Formation of HIV-1 elongation complex containing HIV-1 Tat; HIV elongation arrest and recovery; Pausing and recovery of HIV elongation; Pausing and recovery of Tat-mediated HIV elongation; Tat-mediated HIV elongation arrest and recovery; Tat-mediated elongation of the HIV-1 transcript; Vif-mediated degradation of APOBEC3G
Gene expression (Transcription): Formation of RNA Pol II elongation complex; RNA Polymerase II Pre-transcription Events; RNA Polymerase II Transcription Elongation
Immune System: Antigen processing: Ubiquitination & Proteasome degradation; Inactivation of CSF3 (G-CSF) signaling
Metabolism of proteins: Neddylation; Ribosome Quality Control (RQC) complex extracts and degrades nascent peptide
Cellular responses to stimuli: Oxygen-dependent proline hydroxylation of Hypoxia-inducible Factor Alpha
Developmental Biology: Regulation of expression of SLITs and ROBOs
Gene Ontology:
Molecular function: protein binding; transcription corepressor binding; ubiquitin protein ligase binding
Biological process: target-directed miRNA degradation; transcription initiation at RNA polymerase II promoter; ubiquitin-dependent protein catabolic process via the C-end degron rule pathway; negative regulation of DNA-templated DNA replication; negative regulation of transcription by RNA polymerase II; positive regulation of proteasomal ubiquitin-dependent protein catabolic process; proteasome-mediated ubiquitin-dependent protein catabolic process; protein-containing complex assembly; ribosome-associated ubiquitin-dependent protein catabolic process; transcription elongation by RNA polymerase II; protein ubiquitination
Cellular component: Cul2-RING ubiquitin ligase complex; Cul5-RING ubiquitin ligase complex; elongin complex; cytosol; nucleoplasm; VCB complex; cytoplasm; nucleus; ubiquitin ligase complex
Genetic constraint (gnomAD): Loss-of-function variants: 3 observed, 9.85 expected, observed/expected ratio (o/e) 0.3, 90% interval 0.14 to 0.79. That is too few expected variants to judge how well the gene tolerates losing a copy. Missense variants: 126 observed, 149.02 expected, observed/expected ratio (o/e) 0.85, 90% interval 0.73 to 0.98. Synonymous variants: 84 observed, 63.1 expected, observed/expected ratio (o/e) 1.33, 90% interval 1.12 to 1.6.
Homologues: Orthologues: chimpanzee ELOB (100% identical), macaque TCEB2 (100% identical), rabbit ELOB (98% identical), mouse Elob (97% identical), dog ELOB (97% identical), rat Elobl7 (88% identical), zebrafish elob (86% identical), tropical clawed frog elob (82% identical), pig ELOB (74% identical), rat Elob (74% identical), Drosophila melanogaster EloB (58% identical), Caenorhabditis elegans elb-1 (35% identical).
Diseases named in the same sentence as ELOB in open-access papers:
ELOB is named in the same sentence as 22 diseases in open-access papers, as found by Europe PMC text mining. Sharing a sentence is not in itself a finding about the gene and the disease. The quoted sentences say what the papers report.
breast carcinoma (3 papers, 2018 to 2024). "Moreover, survival analysis indicated that high ELOB expression was associated with worse relapse-free survival (RFS) in all subtypes of breast cancer." (PMID 38653919, 2024). "The result demonstrated that ELOB was over expressed in all molecular subtypes of breast cancer with the highest expression of ELOB in HR + /HER2- subtypes and the lowest in TNBC (P < 0.05)." (PMID 38653919, 2024). "In this study, through bio-informatic analysis of The Cancer Genome Atlas and Fudan University Shanghai Cancer Center database, we demonstrated that ELOB was over-expressed in breast cancer tissues and was related to unfavorable prognosis." (PMID 38653919, 2024). "In order to further elucidate the bio-function of ELOB among patients with breast cancer, bioinformatics analyses of the TCGA database." (PMID 38653919, 2024). "Our study showed the bio-function of ELOB and determined the upregulated expression of ELOB, which revealed the promotional effect of ELOB in breast cancer." (PMID 38653919, 2024). "Remarkably, the downregulation of ELOB led to a significant accumulation of p14/ARF protein across all breast cancer cell lines." (PMID 38653919, 2024). "To elucidate ELOB’s expression dynamics, we analyzed its mRNA levels in breast cancer tissues versus adjacent normal tissues using data from the TCGA and FUSCC databases." (PMID 38653919, 2024). "In the future, it is expected that drugs directed against ELOB will be designed for breast cancer therapy." (PMID 38653919, 2024). "In this study, ELOB was discovered for the first time and it can not only act as a component of the E3 ubiquitin ligase, but also influences the biological behavior of breast cancer." (PMID 38653919, 2024). "In conclusion, ELOB is identified to be a promising innovative target for the drug development of breast cancer by promoting the ubiquitination and degradation of oncoprotein p14/ARF." (PMID 38653919, 2024). "The elevated expression of ELOB in breast cancer suggests its potential as a promising target for anticancer therapy." (PMID 38653919, 2024). "We show that in breast cancer cells Rab40b does bind to the CRL5 E3 ligase complex containing Cullin5, Elongin B, Elongin C, and Rbx2 and that mutations to the Rab40b–SOCS box are sufficient to disrupt this interaction." (PMID 33999101, 2021). "The clonogenic assay and cell viability assay revealed that cell proliferation was suppressed following ELOB knockdown, suggesting that ELOB may serve as a potential anticancer target in breast cancer." (PMID 38653919, 2024). "All in all, our study indicates a novel oncogenic target of breast cancer, ELOB, and targeting ELOB could prevent breast cancer proliferation by suppressing the breakdown of p14/ARF." (PMID 38653919, 2024). "Finally, through analyzing breast cancer tissue microarrays and western blot of patient samples, we demonstrated that the expression of ELOB in tumor tissues was elevated in compared to adjacent normal tissues." (PMID 38653919, 2024). "Then, we confirmed that both in vivo and in vitro, the proliferation of breast cancer cells could be significantly suppressed by the down-regulation of ELOB." (PMID 38653919, 2024). "To investigate in which cells ELOB was predominantly expressed, we performed a single-cell analysis of 8 cell populations from 5 breast cancer cases.The expression of ELOB was observed in tumor cells, T cells, and macrophages among which the highest expression level was observed in tumor cells." (PMID 38653919, 2024). "Although, several studies have explored the relationship between CLR2 and tumors, the role of ELOB in breast cancer remain unclear." (PMID 38653919, 2024). "However, the regulatory role of ELOB in breast cancer remains ambiguous." (PMID 38653919, 2024). "Thus, we hypothesized the up-regulated ELOB might regulate the malignant phenotype of breast cancer." (PMID 38653919, 2024).
breast carcinoma (continued). "Mechanistically, ELOB targets the tumor suppressor protein p14/AKF, leading to the down-regulation of p14/AKF and ultimately promoting the progression of breast cancer." (PMID 38653919, 2024). "Following this, ELOB was targeted for knockdown using siRNA to disrupt the CRL2 complex, and the levels of p14/ARF protein were evaluated via immunoblotting in various human breast cancer cell lines." (PMID 38653919, 2024). "Here, we report that ELOB, identified as a component of CRL2 that promotes degradation of the substrate p14/ARF, was detected to be markedly overexpressed, and was related to unfavorable prognosis in breast cancer." (PMID 38653919, 2024).
glioma (2 papers, 2020 to 2021). A benign or malignant brain and spinal cord tumor that arises from glial cells (astrocytes, oligodendrocytes, ependymal cells). "In this study, we demonstrated that overexpression of the CRL5 components Elongin B, Elongin C, SOCS3 and Rbx2 predicts poor prognosis of glioma and all GBM subclasses." (PMID 32931454, 2020).
renal cell carcinoma (2 papers, 2014 to 2020). "The NR5A1-derived tumors showed 657 unique proteins that participate in Renal cell carcinoma (CRK, ELOB and PAK3) and Homologous recombination (ATM, BRCC3 and MRE11) among others." (PMID 33261069, 2020).
acromegaly (1 paper, 2021). Acromegaly is an acquired disorder related to excessive production of growth hormone (GH) and characterized by progressive somatic disfigurement (mainly involving the face and extremities) and systemic manifestations. "The changes of all ECS-complex proteins in postoperative acromegaly patients and of SOCS2 and EloB in postoperative GHD patients are smaller in comparison to the preoperative groups, which indicates a detectable attenuation of disease severity after surgery." (PMID 33671326, 2021).
colon cancer (1 paper, 2021). "Notably, we observed VHL and ELOB, which are thought to form a protein complex, are top hits that are more essential in KRAS-mutant male colon cancer cells." (PMID 34663427, 2021).
COVID-19 (1 paper, 2021). A disease caused by infection with severe acute respiratory syndrome coronavirus 2. "In CD14+ monocytes, HIF-1 signaling may regulate LDHA, ALDOA, TIMP1, ELOB and IFNGR2, and PPAR signaling may regulate UBC, RXRA, DBI and ACSL1 in COVID-19 patients." (PMID 33936072, 2021).
lung carcinoma (1 paper, 2019). "Based on our data, patients with lung cancers that exhibit loss of function mutations in either CUL5, RNF7, UBE2F or Elongin B that coincide with high expression of MCL1/Bcl-xL could be good candidates for treatment with CDK9i or MCL1i." (PMID 31294695, 2019).
von Hippel-Lindau syndrome (1 paper, 2016). "Of the well-known adaptors of E3 ligase, we selected von Hippel-Lindau syndrome (VHL) and HIV-1 virion infectivity factor (VIF), which are adaptors for the complex including elongin B, elongin C, and cullin-2/5 that possesses E3 ubiquitin ligase activity." (PMID 27322423, 2016).
tumor (13 papers, 2015 to 2025). "VHL’s function as tumor suppressor requires its association with a ubiquitous complex composed of two small proteins, Elongin B and Elongin C, via a linear sequence termed the “BC box,” comprising amino acids 157–172." (PMID 26561808, 2015). "Release of VHL from TRiC requires VHL binding to Elongin B and C and is impaired by tumor-producing mutations that affect the BC-binding site." (PMID 26561808, 2015). "ELOB expression was determined at protein levels though IHC staining in 61 tumor tissues and the paired adjacent normal tissues." (PMID 38653919, 2024). "VHL inhibits the induction of various target molecules of HIFs, such as vascular endothelial growth factor (VEGF) and platelet-derived growth factor (PDGF), by forming a complex (BVC) with elongin B/C and Cullin2, thereby exerting its tumor suppressor effect." (PMID 30902965, 2019). "Furthermore, a positive correlation was observed between ELOB expression and tumor size, with a significant increase from stages T1 to T3 (P < 0.05)." (PMID 38653919, 2024). "Tumor tissues displayed elevated levels of ELOB expression in contrast to adjacent normal tissues." (PMID 38653919, 2024). "Furthermore, the suppressed tumor growth resulting from ELOB knockout was partially restored by concomitant downregulation of p14/ARF, indicating that the antitumor impact of ELOB depletion may be linked to the accumulation of p14/ARF." (PMID 38653919, 2024). "Comparing with the negative control group, the tumor formation was almost repressed in the ELOB knockout group." (PMID 38653919, 2024).
cancer (11 papers, 2014 to 2024). A tumor composed of atypical neoplastic, often pleomorphic cells that invade other tissues. "Additionally, pathway enrichment analysis illustrated that high expression of ELOB was associated with multiple cancer promoting pathways, like cell cycle, DNA replication, proteasome and PI3K − Akt signaling pathway, indicating ELOB as a potential anticancer target." (PMID 38653919, 2024). "EPOP, Elongin B, and Elongin C are often upregulated in cancer and systematic CRISPR screening experiments demonstrated that they are “common essential” in human cancer cell lines, meaning that they are required for efficient proliferation in most human cancer cells." (PMID 35193659, 2022). "For instance, CUL2, RBX1, ELOB, and ELOC are known to interact with PRAME, a substrate-recognition subunit that is overexpressed in a variety of cancers, including HCC." (PMID 35664333, 2022). "To gain a pan-cancer perspective on alterations to these genes, we evaluated the DNA CN status of VHL, CUL2, RBX1, ELOC, and ELOB across 33 cancer types processed by TCGA." (PMID 35664333, 2022). "Targeting ELOB prevented p14/ARF degradation and inhibited cancer cell proliferation." (PMID 38653919, 2024). "Although there is currently no report connecting ELOB with human cancers, our data suggest its potential use to enhance TNBC sensitivity to NAC." (PMID 36142814, 2022). "Moreover, downregulation of EloB expression induced the accumulation of p14/ARF and delayed the turnover of p14/ARF in several human cancer cell lines we examined." (PMID 33504946, 2021).
infection (2 papers, 2014 to 2025). The state of being infected such as from the introduction of a foreign agent such as serum, vaccine, antigenic substance or organism. "Our findings revealed that ELOB downregulation following infection with various viral strains impairs the antiviral activity of CRL2ZYG11B, highlighting virus–host interactions that may disrupt immune responses." (PMID 40135890, 2025). "Interestingly, elongin B is required for viral mRNA expression of various kinetic classes throughout the whole infection cycle." (PMID 25166009, 2014). "Whether pUL79 interacts with host elongation factors such as elongin B to exert its activity, or how pUL79 selectively modulates the transcription elongation complex at late times of infection, requires further exploration." (PMID 25166009, 2014).
cardiac diseases (1 paper, 2024). "Currently, information on ELOB expression in cardiac diseases is limited." (PMID 38970022, 2024).
ELOB also shares sentences with these, for which no sentence is quoted: acute megakaryoblastic leukemia (1 paper); breast tumors (1); colorectal cancer (1); congestive heart failure (1); dengue (1); glioblastoma (1); malaria (1); Obesity (1); ovarian carcinoma (1); triple-negative breast carcinoma (1).